STING1 (stimulator of interferon response cGAMP interactor 1)
Diseases named in the same sentence as STING1 in open-access papers (continued):
Sharing a sentence is not in itself a finding about the gene and the disease.
peripheral vascular disease (1 paper, 2021). Any disorder affecting blood flow through the veins or arteries outside of the heart. "We identified 5 patients (3 kindreds) with predominantly peripheral vascular disease who harbor 3 novel STING1 variants, p.H72N, p.F153V, and p.G158A." (PMID 33833757, 2021).
thymoma (1 paper, 2022). A neoplasm arising from the epithelial cells of the thymus. "In CESC, ESCA, GBM, LUSC, and thymoma (THYM), RRM2 had a negative correlation with marker genes of immune activating genes, such as VSTR, TNFSF14, TNFRSF14, and STING1." (PMID 36518297, 2022).
tumor (2,467 papers, 2013 to 2026). "The ER stress response was dependent on STING expression as reduced response was associated with Sting1-knockout CINhigh tumours even in the presence of ER stress inducer, tunicamycin (TM)." (PMID 38253764, 2024). "Poor Sting1 expression in tumors has been associated with poor prognosis, though Sting1 expression in tumor stroma has shown a greater correlation with patient prognosis." (PMID 39622844, 2024). "Coculture of CINhigh tumour cells with macrophages led to significant reduction in relative arginase expression upon loss of cancer cell Cgas or Sting1." (PMID 37612508, 2023). "In addition, apoptotic tumor cells activate the STING1 pathway in tumor-associated macrophages (TAMs), thereby enhancing antitumor immune responses." (PMID 34078874, 2021). "Notably, some cancer cells from each tumor origin lack cGas and/or Sting1 and so may be deficient in innate sensing following radiation, consistent with observations in other cancers." (PMID 39622844, 2024). "Among the top-ranked variants were rs11554776, rs78233829, and rs7380824 in STING1, which demonstrated functional impacts on intrinsic cGAS-STING1-IFN signaling in cancer cells and potential influences on tumor immunity." (PMID 41569853, 2026). "We found that tumor cell clusters with higher CGAS or STING1 expression exhibited stronger receptor-ligand interactions with T cells." (PMID 40735041, 2025). "Results showed that the tumor nodules emerged earlier and tumors were larger in the Sting1−/− group, indicating that endogenous STING activation promotes Vγ4 γδ T cell‐mediated anti‐tumor immunity in vivo." (PMID 39573933, 2025). "In our experimental model of P. salmonis infection, STING1 expression showed early activation and subsequent repression, mirroring suppression patterns observed in chronic viral models and tumor microenvironments." (PMID 40607404, 2025). "Knockout of STING1 attenuated the induction of IRGs as well as the anti-tumor effect of DOT1L inhibition in MM cells." (PMID 41299712, 2025). "As expected, we found that expression of TMEM173/STING1 decreased across DDR clusters in single tumor cells." (PMID 40114214, 2025). "Subsequently, we wished to determine if immunity was enhanced due to activation of stimulator of interferon response cGAMP interactor 1 (STING) pathways in the treated tumor cells." (PMID 40552293, 2025). "Based on the expression levels of CGAS or STING1 in tumor cell clusters, the samples were divided into high- and low-expression groups." (PMID 40735041, 2025). "CIN inhibition or Cgas/Sting1 knockout resulted in CD8+ cytotoxic T cell infiltration in such tumours." (PMID 38253764, 2024). "Despite systemic depletion in STING1-KO mice, COX inhibition by INDO effectively limited tumor growth in irradiated 4T1 tumors, emphasizing the importance of the localized STING response within the tumor." (PMID 38912586, 2024). "Spatial immunological changes including augmented lymphoid infiltration into the tumor epithelium and locally increased cGAS/STING1 and type I IFN gene expression were observed in radiation-indomethacin–treated 4T1 tumors." (PMID 38912586, 2024). "Further multivariate analysis has confirmed this tumour differentiation and STING1 expression as the independent prognostic biomarker of pCCA." (PMID 37488750, 2023). "Expression of SMAD4 and STING1 were downregulated in CCA tumours and STING1 expression correlated with SMAD4 expression." (PMID 37488750, 2023). "The result revealed that the mRNA expression level of SMAD4 and STING1 was significantly downregulated in eCCA tumour tissues compared to the para‐tumour tissue." (PMID 37488750, 2023). "The findings revealed a reduction in the expression of both SMAD4 and STING1 in tumour samples, along with a significant correlation between the expressions of SMAD4 and STING1." (PMID 37488750, 2023).
tumor (continued). "Further research is needed to clarify the role of STING1 in regulating ferroptosis in different immune cells within the tumor microenvironment." (PMID 34078874, 2021). "Tumor cells with increased expression of CGAS or STING1 showed enhanced interactions with T cells." (PMID 40735041, 2025). "Furthermore, we evaluated the tumor immunogenicity of STING1 molecule expression in the Cancer Genome Atlas (TCGA) pan-cancer datasets." (PMID 40452917, 2025). "Furthermore, elevated expression levels of CGAS and STING1 in tumor cells promoted their interaction with T cells, which is crucial for enhancing the efficacy of immunotherapy." (PMID 40735041, 2025). "To further confirm the potential role of endogenous STING signaling in regulating γδ T cell‐mediated tumor immunity, we applied the in vitro co‐culture system with wild‐type (WT) and Sting1−/− Vγ4 γδ T cells against a series of tumor cell lines." (PMID 39573933, 2025). "However, expression of ER stress cytokines in Sting1-knockout CINhigh tumours resulted in enhanced metastasis." (PMID 38253764, 2024). "Together, these results suggest therapeutically beneficial effects of localized STING antitumor response following radiation/NSAID combination treatment and are supported by GSE37751 database probability of survival examining the influence of tumor COX2 on STING1." (PMID 38912586, 2024). "Importantly, depleting cancer cell Sting1 in CINhigh tumours abolished many of the effects of CIN on the TME, ultimately restoring it to a CINlow-like state." (PMID 37612508, 2023). "However, the promoter regions of cGAS and STING1 in tumour cells are usually highly methylated and silenced or have a loss of function mutation." (PMID 37488750, 2023). "However, none of the well‐known risk factors, such as age, gender, tumour size, tumour differentiation, T stage, N stage, M stage, TNM stage, neural invasion and cancer thrombus, were found to correlate with STING1 expression in iCCA and pCCA." (PMID 37488750, 2023). "Enpp1H362Amice retarded E0771 tumor growth to a similar degree as Enpp1−/− mice, as compared to WT mice and the tumor slowing effects in Enpp1H362A mice were completely abolished in the Sting1 knockout background." (PMID 38117852, 2023). "An acute activation of STING1 is beneficial for antitumor therapy, and chronic activation of STING1 may mediate inflammation that supports tumor growth." (PMID 34078874, 2021). "To further investigate the functional characterization of cGAS and STING in the tumor microenvironment, we utilized the TISIDB database to explore the correlation between CGAS and STING1 expressions and immune cell abundances." (PMID 40735041, 2025). "Moreover, the activation of STING1 and interferon alpha suggests a sustained innate immune activation program, which, under chronic stimulation may promote immune exhaustion, tolerance or compensatory suppression of anti-tumor responses." (PMID 41514627, 2025). "The T cell abundance and tumor-T cell interactions in different CGAS and STING1 expression groups were analyzed using bulk RNA-seq and scRNA-seq data from open databases." (PMID 40735041, 2025). "This unique mechanism relies on the participation of tumor-infiltrating T cells and is dependent on the coordinated activation of stimulator of interferon response CGAMP Interactor 1 (STING) and type I interferon responses." (PMID 40083710, 2025). "In this study, we conducted an analysis of STING1 and SMAD4 expression in both CCA tumour tissues and adjacent normal tissues." (PMID 37488750, 2023). "And suppression of CIN or knockout of either Cgas or Sting1 in CINhigh cells enhanced CD8+ T cell migration and led to increased tumour cell killing by pan-T cells, CD8+ T cells or natural killer (NK) cells." (PMID 37612508, 2023). "In conclusion, our study has provided evidence that the expression of both STING1 and SMAD4 is downregulated in CCA tumour tissues when compared to the corresponding para‐tumour tissues." (PMID 37488750, 2023).
tumor (continued). "Expression of STING1 and SMAD4 were downregulated in tumour tissues of iCCA, pCCA and dCCA compared to the para‐tumour tissue." (PMID 37488750, 2023). "The identified potential tumor suppressor genes included DAG1, SLC39A8, TMEM173/STING1, RDX, TJP1, CTNNB1, and SMC3." (PMID 36499305, 2022). "These augmented anti-tumor effects were not cancer cell intrinsic, but instead activated the cGAS/STING1 pathway and enhanced infiltration of tumor-killing immune cells." (PMID 40105196, 2025). "Mechanistic investigations revealed that ferroptosis-induced oxidative DNA damage results in the release of 8-hydroxyguanosine (8-OHG), which activates the TMEM173/STING1-dependent DNA sensing pathway, promoting macrophage recruitment and activation during the early stages of tumor formation." (PMID 41293165, 2025). "This variant was in high LD with rs1131769 (r2 = 0.93), a missense variant in STING1 which was an identified locus for overall HNSCC risk (OR = 1.13 (1.09, 1.18), pmeta = 2.38 × 10−10), and seemed to be driven by non-HPV driven tumours." (PMID 41038832, 2025). "While WT had slower primary tumor growth as Sting1−/−mice, the two genotypes had similar lung metastatic burden, indicating that endogenous ENPP1 activity in the tissue fully blocks STING-mediated immunological protection specifically against metastasis." (PMID 38117852, 2023). "To rule out potential off-target effects from CRISPR–Cas9-mediated KO, we depleted Sting1 using short hairpin RNA (shRNA) and observed a similar reduction in lung metastasis with no impact on primary tumour formation." (PMID 37612508, 2023). "Nevertheless, a more comprehensive approach is essential to enhance the pro-ferroptotic effect of STING1 without changing its beneficial mechanism in tumor immunity." (PMID 34195205, 2021). "However, in CD105-negative CAFs, the STING1, NFκB, IL-6, TNF-α, JAK2, and LTBR signals observed high expression and remarkably performed tumor suppression." (PMID 35265630, 2021). "By maintaining inflammation-related tumorigenesis, this chronic activation of STING1 triggered by ferroptotic DNA damage ultimately promotes KRAS-driven pancreatic ductal adenocarcinoma in mice, highlighting the dark side of ferroptosis in tumor immunity." (PMID 34078874, 2021). "Notably, the 5-FU mediated effects on tumor cells were not exerted directly, but instead activated the cGAS/STING1 pathway and promoted anti-tumor immunity." (PMID 40105196, 2025). "In the case of perihilar CCA (pCCA), tumour size, tumour differentiation, STING1 expression, SMAD4 expression, and the co‐absence of STING1 and SMAD4 expression were identified as prognostic factors." (PMID 37488750, 2023). "To date, the literature supports the tumor suppressor functions of DAG1, SLC39A8, TMEM173/STING1, TJP1, CTNNB1, and SMC3, but not RDX." (PMID 36499305, 2022). "The activity of caspase-3 (an apoptosis marker) and the mRNA expression of STING1, MFN1, and MFN2 in tumor extracts was not changed by IKE." (PMID 34195205, 2021).
cancer (1,390 papers, 2014 to 2026). A tumor composed of atypical neoplastic, often pleomorphic cells that invade other tissues. "Deciphering the actual functionality of STING1 alleles is thus essential also to drive the precision-medicine approach to oncologic patients’ cancer immunotherapy." (PMID 37945588, 2023). "Further, 5-FU can mediate aspects of its anti-cancer effects through the immune-activating cGAS/STING1 pathway." (PMID 40105196, 2025). "CGAS and STING1 also play essential roles in maintaining genome integrity and the initiation and progression of cancer." (PMID 40463121, 2025). "To identify key components involved in MHC-I upregulation via CDK12/13 antagonism, we knocked out Cgas, Sting1 (encoding STING), Ifnar1 (encoding IFNAR1), or Rela (encoding p65) in cancer cell lines." (PMID 40955658, 2025). "Next, as STING1 expression has been shown to be repressed across many cancers through epigenetic mechanisms, we used CellMiner-SCLC and found a significant correlation between STING1 expression and enrichment of H3K27ac at the STING1 promoter region." (PMID 40627448, 2025). "Of note, compared to mice inoculated with wild type B16 cells, both Cgas and Sting1 knockout in carcinoma cells mitigated the CD11b+ and F4/80+ myeloid cells infiltration in liver." (PMID 39737867, 2025). "Methylation of the STING1 or CGAS promoter has been reported in different cancers and inhibitors of DNA methyltransferase restored STING signaling." (PMID 39469633, 2024). "In contrast to the restricted expression of Enpp1, the ability to respond to cGAMP via Sting1 expression was widely shared between cancer cells and infiltrating cell types in this dataset (Fig. 1bii)." (PMID 39622844, 2024). "The significance of STING1 gene in tissue inflammation and cancer immunotherapy has been increasingly recognized." (PMID 39291958, 2024). "Beyond somatic mutations that often occur in cancer, the human gene encoding STING protein, TMEM173 (STING1), holds great genetic heterogeneity; R232, HAQ (R71H-G230A-R293Q) and H232 are the most common alleles." (PMID 37945588, 2023). "A second saRNA NBT, designed to upregulate STING (stimulator of interferon response cGAMP interactor 1) aims to address immune evasion and improve the effectiveness of existing cancer immunotherapies and is now at early developmental stages at MiNa." (PMID 36250017, 2022). "Silencing of STING1 is common in ALT+ cancer cells in order to prevent the activation of innate immune responses by the elevated level of extrachromosomal telomeric repeats (ECTR)." (PMID 34771533, 2021). "The studied G4 binders (pyridostatin and PhenDC3) can induce an increase of micronuclei triggering the activation of the cytoplasmic STING (stimulator of interferon response cGAMP interactor 1) signaling pathway in human and murine cancer cells." (PMID 34139015, 2021). "Overall, these in vitro and in vivo data indicate that STING1 activation induced by host DNA damage can trigger ADCD to remove cancer cells or other stressed cells." (PMID 34078874, 2021). "Activating the STING1 pathway is a promising strategy for cancer immunotherapy." (PMID 39291958, 2024). "Reduced metastasis by the STING inhibitor did not match complete Sting1 KO, and this might be due to incomplete target exposure by the drug or dichotomous contributions of cancer cell and host cell STING, both of which would be inhibited with drug treatments." (PMID 37612508, 2023). "Moreover, STING1 participated in several cancer-related processes such as apoptosis, pyroptosis, necroptosis, and ferroptosis, implying its potential role in molecular targeting for preventing the progression of malignancies." (PMID 36224658, 2022). "In addition, the sulfated glycosaminoglycans (sGAGs) can bind the TM domain of STING1 and promote STING1 clustering in Golgi and subsequent activation in cancer cells (THP1, HeLa, and HT1080 cells)." (PMID 35371032, 2022).
cancer (continued). "Thus, the STING1-related ferroptosis pathway is a potential therapeutic target of cancer and tissue damage." (PMID 34078874, 2021). "Thus, cancer is rare in armadillos, and possibly pangolins, which may be related to the loss of the evolutionary CGAS and STING1 genes." (PMID 40463121, 2025). "As anticipated, knockout (KO) of Cgas, Sting1, or Ifnar1 abolished MHC-I induction by CDK12/13 antagonism in various cancer models." (PMID 40955658, 2025). "Our analysis indicated a positive correlation between B3GNT5 and immune activation markers, including CD276, PVR, NT5E, STING1, and TNF-SF18, as well as immunosuppressive genes TGF-ΒR1, IL-10PR, KDR, CD274, PDCD1LG2, IL-10, and IDO1 in the pan-cancer cohort." (PMID 39671359, 2024). "SQSTM1 is required for STING1-dependent autophagy to inhibit M. tuberculosis infection in macrophages, but SQSTM1 is dispensable for STING1-mediated autophagy in HeLa cancer cells." (PMID 35371032, 2022). "The results revealed that CD161 was positively correlated with marker genes of exhausted T cells, immune activating genes, and immunosuppressive genes in pan-cancer, such as TIGIT, PDCD1, LAG3, CTLA4, STING1, CD96, and IDO1." (PMID 34305920, 2021). "We found that CD161 was positively correlated with marker genes of exhausted T cells, immune activating genes, and immunosuppressive genes in pan-cancer such as TIGIT, PDCD1, LAG3, CTLA4, STING1, CD96, and IDO1." (PMID 34305920, 2021).